FTH1 (ferritin heavy chain 1)
Diseases named in the same sentence as FTH1 in open-access papers (continued):
Sharing a sentence is not in itself a finding about the gene and the disease.
glioblastoma (14 papers, 2018 to 2025). The most malignant astrocytic tumor (WHO grade IV). "Ferritin heavy chain 1 (FTH1), the iron regulatory protein, is increasingly linked to high tumor grade and poor survival outcomes in glioblastoma." (PMID 39001407, 2024). "Glioma initiating cells (GICs), a small population of stem-like cells implicated in therapeutic resistance and glioblastoma recurrence, have recently been shown to exhibit increased FTH1 expression." (PMID 31491006, 2019). "Elevated expression of the iron regulatory protein, ferritin heavy chain 1 (FTH1), is increasingly being associated with high tumor grade and poor survival outcomes in glioblastoma." (PMID 31491006, 2019). "Another study reported the design of liposomal nanoplatforms loaded with ferritin heavy chain 1 (FTH1)-siRNAs to treat radioresistant glioblastomas." (PMID 36358663, 2022). "We therefore wanted to determine the effect of FTH1 loss on GICs isolated from relatively radio sensitive (proneural, PN) and radio resistant (Mesenchymal, MES) glioblastomas." (PMID 31491006, 2019). "Although we have previously shown efficacy of FTH1 siRNA in a subcutaneous glioblastoma model using astrocytoma cells, we found this liposomal formulation had poor transfection efficiency in GICs." (PMID 31491006, 2019). "Our study provides further evidence to support the role of FTH1 as a promising target in glioblastoma." (PMID 31491006, 2019). "Xenograft studies showed that shRNA-mediated FTH1 or FTL knockdown suppressed tumorigenesis of glioblastoma cells." (PMID 28793787, 2018). "However, only GICs from pro-neural glioblastoma showed marked increase in radiosensitivity upon FTH1 downregulation demonstrated by decreased cell viability, impaired DNA repair and reduced colony formation subsequent to radiation." (PMID 31491006, 2019). "Therefore, in this study we developed a liposomal formulation to enable the in vitro delivery of FTH1 siRNA in patient xenograft derived GICs from glioblastomas with pro-neural and mesenchymal transcriptional signatures to interrogate the effect of FTH1 downregulation on their radiation sensitivity." (PMID 31491006, 2019). "Given the already known role of NCOA4 in ferritin degradation, targeting the COPZ1/NCOA4/FTH1 axis may be a promising therapeutic strategy for the treatment of human glioblastoma (GBM)." (PMID 35756082, 2022).
melanoma (14 papers, 2019 to 2025). A malignant, usually aggressive tumor composed of atypical, neoplastic melanocytes. "A significant decrease in GPX-4 and/or FTH-1 expression levels was noted in all three BRAF-mutated melanoma cell lines, with a particularly pronounced effect seen with cabotegravir treatment." (PMID 38338893, 2024). "We found that DTIC significantly affected the expression levels of various metabolic enzymes, including ADSL, PYCR1, PRODH, and FTH1, in melanoma cells." (PMID 37976135, 2023). "In the study of the proteomics in human metastatic melanoma cells knocking down FTH1, 200 differential proteins were found, mainly distributed in metabolic pathways related to tumor progression and metastasis." (PMID 38025726, 2023). "Analysis of bone tissues using qPCR showed that melanoma metastasis caused degradation of ferritin light chain 1 (Ftl1), while ferritin heavy chain 1 (Fth1) was not affected." (PMID 39814705, 2025). "Furthermore, after TGF-β1 induces EMT in melanoma cells, the expression of ferritin heavy chain 1 (FTH1) decreases, leading to an increase in labile iron pool (LIP) and intracellular ROS generation." (PMID 38594623, 2024). "Knockdown FTH1 can inhibit the growth and invasion of melanoma." (PMID 38025726, 2023). "Gray showed that melanoma cells secreting FTH1 could activate Tregs to produce interleukin-10 and suppress the immune response in vitro." (PMID 33864445, 2021). "Melanoma-A consisted of CD63, PMEL, and S1000A1, while Melanoma-B consisted of S100B, FTH1, and AEBP1 expression." (PMID 33535416, 2021). "A core group of differentially expressed genes (FTH1, FTL, HSPA8, HSP90AA1, and HSP90B1) was recurrently identified within significantly enriched pathways across TCGA melanoma samples and clinical cohorts." (PMID 32296058, 2020).
pancreatic cancer (14 papers, 2021 to 2025). "To further confirm this finding, we generated PROGgeneV2 Kaplan–Meier survival curves by using data from The Cancer Genome Atlas (TCGA) and analyzed the association of the FTH1/FTL expression ratio with the overall survival of patients with pancreatic cancer." (PMID 39294443, 2024). "The main discovery is that high FTH1 expression is associated with worse survival in pancreatic cancer patients, suggesting that targeting FTH1 could be a promising treatment for this aggressive cancer." (PMID 39294443, 2024). "To further explore how FTH1 is linked to the reprogramming of proline metabolism in pancreatic cancer cells, we measured the protein expression of proline metabolism-associated molecules, PYCR1 and PRODH, in control and shFTH1-infected SUIT-2 cells through Western blotting." (PMID 39294443, 2024). "Hence, we also determined whether the FTH1 or FTL gene was correlated with a set of ferroptosis genes that were revealed to be highly associated with increased risks for pancreatic cancer." (PMID 34711879, 2021). "We further performed qRT-PCR on five selected ferroptosis-related genes (HMOX1, CHAC1, SLC3A2, SLC7A11, and FTH1) in pancreatic cancer cells after 12 and 24 h of CBC treatment." (PMID 40790027, 2025). "The autophagy results in the degradation of ferritin-heavy polypeptide 1 (FTH1) and an increase in the intracellular free iron levels, thereby promoting ferroptosis in pancreatic cancer cells." (PMID 39519572, 2024). "We subsequently performed rescue experiments on FTH1-overexpressing shFTH1-infected SUIT-2 cells to further confirm the role of FTH1 in proline metabolism dysregulation and pancreatic cancer progression." (PMID 39294443, 2024). "Crucially, this finding also demonstrated that DFX exerts its antiproliferative effects on pancreatic cancer cells by inhibiting FTH1 expression, suggesting a novel role for DFX in the modulation of proline metabolism." (PMID 39294443, 2024). "The current results are consistent with the online database data: strong FTH1 but not FTL expression is significantly correlated with worsened survival of patients with pancreatic cancer as well as in those with high FTH1–KRAS co-occurrence." (PMID 39294443, 2024). "We observed that while miR-2355-5p and miR-5000-3p expression was generally downregulated in pancreatic cancer tissues, FTH1 knockdown in SUIT-2 cells led to the upregulation of miR-2355-5p and miR-5000-3p." (PMID 39294443, 2024). "In this study, FTH1 expression was upregulated in most KRAS-mutant human pancreatic cancer cells and clinical pancreatic cancer tissues, contributing to PDAC progression through positive crosstalk with PYCR1 and promoting proline metabolism dysregulation." (PMID 39294443, 2024). "A clonogenic assay was used to determine the long-term effects of FTH1 on pancreatic cancer cell proliferation and the survival of individual cells until they grew into colonies." (PMID 39294443, 2024).
pancreatic cancer (continued). "Taken together, these results suggest that DFX treatment significantly affects pancreatic cancer cell viability, potentially through the modulation of FTH1 expression and alterations in proline and P5C metabolism, suggesting a promising therapeutic avenue for targeting pancreatic cancer." (PMID 39294443, 2024). "The results revealed that hTERT-HPNE cells had relatively low FTH1 expression, whereas the FTH1 levels in the KRAS-mutant pancreatic cancer cell lines Mia PaCa-2 and SUIT-2 were approximately 18- and 13-fold higher, respectively, than those in hTERT-HPNE cells." (PMID 39294443, 2024). "To further confirm the role of FTH1 in KRAS-mutant-mediated pancreatic cancer cell growth, we assessed whether FTH1 overexpression can restore the effect of FTH1 knockdown on cell viability." (PMID 39294443, 2024). "The results also confirmed that high FTH1 expression is negatively correlated with the overall survival of patients with pancreatic cancer: patients with a higher FTH1/FTL expression ratio had significantly lower overall survival than did those with a lower FTH1/FTL expression ratio." (PMID 39294443, 2024). "Notably, FTH1 expression was strongly associated with the TNM stage, demonstrating that FTH1 is strongly expressed in human pancreatic tumor tissues and that its expression is positively correlated with a poor pancreatic cancer prognosis." (PMID 39294443, 2024). "mRNA expressions of neither FTH1 nor FTL were significantly associated with clinical stages of pancreatic cancer." (PMID 34711879, 2021). "Deferasirox (DFX), an iron chelator, was also found to have an antiproliferative effect on pancreatic cancer cells via the suppression of FTH1 expression, suggesting that FTH1 expression or activity may be exploited as an effective therapeutic tool to target KRAS-mutant PDAC." (PMID 39294443, 2024). "Here, we found that FTH1 may be a promising therapeutic target for KRAS-mutant pancreatic cancer." (PMID 39294443, 2024). "We previously reported that FTH1 is strongly expressed in many KRAS-mutant pancreatic cancer cells; thus, extracellular and intracellular glutamine and glutamate contents were measured to evaluate whether FTH1 is associated with a metabolic shift in glutamine metabolism." (PMID 39294443, 2024). "Recent studies have suggested that FTH1 and FTL are associated with cancer risk and that this risk may vary with cancer type; therefore, we hypothesized that differential FTH1 and/or FTL expression in ferritin is involved in pancreatic cancer risk." (PMID 39294443, 2024). "Moreover, we showed that correlations between expressions of FTH1 and the ferroptosis regulators, FDFT1 and LPCAT3, may be linked to initiation of pancreatic tumors." (PMID 34711879, 2021). "Taken together, these findings highlight the critical regulatory axis of FTH1 and PYCR1 in pancreatic cancer cell metabolism and survival, suggesting a shared pathway that influences malignancy and potential treatment targets in PDAC." (PMID 39294443, 2024). "In this study, we elucidated new mechanistic pathways highlighting the interplay between FTH1 and PYCR1, which appears to form a self-reinforcing loop that collectively drives the progression of KRAS-mutant pancreatic cancer." (PMID 39294443, 2024). "These stains show the effects of DFX on the tumor microenvironment, particularly regarding collagen deposition and the expression of FTH1 and PYCR1, which are key to understanding the mechanistic impact of DFX on pancreatic cancer cells and tissues." (PMID 39294443, 2024). "Ferritin, comprising heavy (FTH1) and light (FTL) chains, is the main iron storage protein, and pancreatic cancer patients exhibit elevated serum ferritin levels." (PMID 39294443, 2024). "The evidence of safety and efficacy from clinical trials supports the feasibility of selectively targeting FTH1 in cancer therapy, opening up new avenues for treatment strategies for KRAS-mutant pancreatic cancer." (PMID 39294443, 2024).
pancreatic cancer (continued). "Our findings suggest that the interaction between FTH1 and PYCR1 leads to aberrant proline metabolism, subsequently inducing apoptosis in KRAS-mutant pancreatic cancer cells." (PMID 39294443, 2024). "We thus examined messenger (m)RNA expressions of FTH1 and FTL in pancreatic cancer patients using Oncomine datasets." (PMID 34711879, 2021). "We also observed that FTH1 and PYCR1 overexpression in SUIT-2/shFTH1#4 cells considerably rescued the inhibitory effects of 10 μM and 20 μM DFX after 72 h, suggesting that FTH1/PYCR1 expression is key for the anti–pancreatic cancer activity of DFX." (PMID 39294443, 2024). "Collectively, these results suggest a complex regulatory network in which FTH1 influences pancreatic cancer progression by modulating PYCR1 expression, which in turn may be part of a feedback loop involving proline that controls the effects of FTH1, thus impacting cell viability and proliferation." (PMID 39294443, 2024). "Furthermore, treatment with DFX substantially decreased FTH1 and FTL protein levels, indicating that DFX may exert its inhibitory effects on pancreatic cancer cell growth through the downregulation of FTH1 activation." (PMID 39294443, 2024). "Consequently, these findings suggest that inhibition of FTH1, possibly through the use of DFX or similar agents, could be a viable strategy to potentiate therapeutic outcomes in pancreatic cancer." (PMID 39294443, 2024). "Moreover, a correlation analysis of CBS and FTH1 showed a significant positive correlation in the controls but a negative correlation in G2 pancreatic tumors." (PMID 34711879, 2021).
leukemia (13 papers, 2020 to 2025). A malignant (clonal) hematologic disorder, involving hematopoietic stem cells and characterized by the presence of primitive or atypical myeloid or lymphoid cells in the bone marrow and the blood. "FTH1 promotes leukemia cell proliferation via the ferroptosis pathway, serving as a potential risk factor influencing the prognosis of pediatric non-M3 AML." (PMID 40725394, 2025). "Our work here shows that MYB can confer resistance to sorafenib via upregulating FTH1 and inhibiting sorafenib-induced ferroptosis in human leukemia." (PMID 40725394, 2025). "In this study, we found that MYB can inhibit sorafenib induced ferroptosis in human leukemia K562 cells through upregulating FTH1, conferring sorafenib resistance to leukemia cells." (PMID 40725394, 2025). "High expression of FTH1 can promote tumor cell proliferation and migration and inhibit ferroptosis in leukemia." (PMID 40725394, 2025). "This is consistent with our findings that FTH1 knockout inhibits cell proliferation and migration while enhancing the effect of sorafenib, thereby inducing ferroptosis in leukemia cells." (PMID 40725394, 2025). "Here, we showed that MYB can upregulate FTH1, inhibit ferroptosis in human leukemia cells." (PMID 40725394, 2025). "Rescue experiments confirmed that FTH1 is required for MYB induced sorafenib resistance and ferroptosis inhibition in human leukemia cells." (PMID 40725394, 2025). "From the expression levels of FTH1 in normal, AML, MDS, and ALL cells, levels in AML leukemia cells were increasingly higher than those in normal cells (P=0.00028)." (PMID 36818670, 2022). "Although the functional consequences of this stratification are not clear in the context of actual ferroptosis induction, we reasoned that decreased GPX4, FTH1 and SLC7A11 levels might facilitate ferroptosis induction in leukemia cells." (PMID 40382332, 2025). "By inhibiting the FTH1 expression, the proliferation of AML leukemia cells could be negatively affected, resulting in a better prognosis of childhood non-M3 AML." (PMID 36818670, 2022). "Multidrug-resistant (MDR) K562/adriamycin (ADM) leukemia cells have higher GSH levels and iron-regulatory protein 2 (IRP2), transferrin receptor, ferritin heavy chain 1 (FTH1), and GPX4 expression, which may enhance their antioxidantcapacity and protect K562/ADM cells from ferroptosis." (PMID 39060524, 2024). "Furthermore, we assayed expression levels of FTH1 in MOLM-13 and THP-1 cells after induction and inhibition of ferroptosis by real-time quantitative PCR, which showed that upregulated FTH1 expression promoted proliferation and inhibited apoptosis in leukemia cells." (PMID 36818670, 2022). "Using the expression level of FTH1 and FTL to reflect iron overload is not a specific indicator for iron overload in leukemia and has limitation." (PMID 40881683, 2025).
liver cancer (13 papers, 2020 to 2025). An epithelial or non-epithelial malignant neoplasm that arises from the liver. "We also examined the top most informative features and observed that the most informative nullomers were found at liver cancer-associated genes, including FTH1, EEF2, TMSB10, ACTB and the long non-coding RNA MALAT among others." (PMID 38351138, 2024). "FTH1 is closely associated with malignant tumors such as breast and liver cancers as well as hematological malignancies." (PMID 36818670, 2022). "We further detected 60 pairs of liver cancer tissues by immunohistochemistry, and found that the expression of FTH1, FTL in tumor tissues was significantly higher than that in para-tumor tissues." (PMID 37555866, 2023). "FTH1 was used as an MRI reporter gene in liver cancer, which can be used for the diagnosis and treatment of early liver cancer; also, with additional iron added, it was more efficient and safer in nasopharyngeal carcinoma." (PMID 38025726, 2023). "Decreased ISCU expression can reduce the translation of the iron storage protein FTH1 and lead to iron accumulation in liver cancer." (PMID 37681451, 2023). "Additionally, FTH1 is an unfavorable prognostic marker in renal cancer, head and neck cancer and liver cancer." (PMID 36307127, 2023). "-Inhibits the proliferation of liver cancer HUH7 and HCCLM3 cells by activating ferritinophagy in cancer cells and modulating the NCOA4/FTH1/LC3II signaling pathway for increase ferroptosis." (PMID 38397559, 2024). "FTH1, FTL were significantly overexpressed in the three liver cancer cell lines compared with normal liver cells." (PMID 37555866, 2023). "The varied expression levels of DEFRGs between the tumor and control groups in the TCGA-LIHC liver cancer dataset were compared, where ZFP36, NCOA4, FTH1, FTL, TNF, and PCBP1 were matched with the TCGA transcriptome data." (PMID 37555866, 2023). "According to our experimental results, caryophyllene oxide can induce ferritinophagy in tumor cells by regulating the NCOA4/FTH1/LC3II signaling pathway, which leads to ferroptosis and the inhibition of the growth of the liver cancer cells, HCCLM3 and HUH7." (PMID 35899120, 2022). "These genes include quinone oxidoreductase 1 (NQO1), HO-1 and ferritin heavy chain 1 (FTH1), all of them may inhibit ferroptosis in liver cancer cells." (PMID 40689204, 2025). "Finally, we validated the key prognostic genes FTH1, FTL, using qRT-PCR, and found that the expression of FTH1 and FTL was significantly higher in various liver cancer cells than in normal liver cells." (PMID 37555866, 2023).